CAMK1D (calcium/calmodulin dependent protein kinase ID)
Diseases named in the same sentence as CAMK1D in open-access papers (continued):
Sharing a sentence is not in itself a finding about the gene and the disease.
depression (2 papers, 2023 to 2024). "Single-nucleotide polymorphisms (SNPs) in CAMK1D have been linked to depressive episodes and suicide attempts in patients with depression." (PMID 39684694, 2024). "RNA editing modifications were analyzed using a panel of eight genes (CAMK1D, GAB2, IFNAR1, KCNJ15, LYN, MDM2, PDE8A, PRKCB) that we previously identified and whose editing combinations were suggested as biomarkers to distinguish BD from unipolar depression and subcategories of BD patients." (PMID 39684694, 2024).
invasive breast carcinoma (2 papers, 2022). A carcinoma that infiltrates the breast parenchyma. "Similarly, it has been reported that Camk1d was overexpressed when amplified in invasive breast carcinomas." (PMID 35391793, 2022). "In addition, tumor-related studies have found that CAMK1D expression is higher in invasive breast cancer than in situ breast cancer and that overexpression of CAMK1D in breast epithelial cells promotes molecular and phenotypic alterations in epithelial–mesenchymal transition (EMT)." (PMID 35494053, 2022).
leukemia (2 papers, 2024 to 2025). A malignant (clonal) hematologic disorder, involving hematopoietic stem cells and characterized by the presence of primitive or atypical myeloid or lymphoid cells in the bone marrow and the blood. "It is possible, therefore, that the increase in the Ly6g + and Camk1d + immature neutrophils is a result of this increased mobilization in the presence of leukemia." (PMID 38730491, 2024). "To gain a better understanding of the biological function of the leukemia induced neutrophils, we analysed the differential gene expression during leukemia progression, focusing on the Ly6g + and Camk1d + neutrophils that showed increased levels in the leukemic mice." (PMID 38730491, 2024). "In summary, these leukemia induced Camk1d + neutrophils undergo transcriptional reprogramming, and the differentially expressed genes and pathways identified may be associated with their function in immune suppression." (PMID 38730491, 2024). "Of the upregulated genes, Syne1, Atxn10 and Dach1 show activation as early as Day 11, while Ngp, Abca13, Adpgk, Mmp8 and Lcn2 were more significantly upregulated in the later stage, D14 neutrophils,which suggests a sequential activation in Camk1d + neutrophils during leukemia progression." (PMID 38730491, 2024). "Clusters 9 (Camk1d + Neutrophils) and 13 (Ly6g + neutrophils) show a close correlation with leukemia progression with a progressive increase (> 10-fold) of Ly6g + neutrophils by Day 14 in BBC2 engrafted mice compared with naive mice (5.25% versus 0.47% respectively)." (PMID 38730491, 2024). "Four of these genes were reported for leukemias (IRS1, RUNX2, CCDC50 and ROBO3) and four others were reported to be involved in other types of cancers (NSG1, CAMK1D, CD3E, KLF8)." (PMID 41146244, 2025).
glioblastoma (1 paper, 2022). The most malignant astrocytic tumor (WHO grade IV). "The regulation of CAMK1D in glioblastoma is a complex network involving multiple genes." (PMID 35494053, 2022).
HIV-1 infection (1 paper, 2023). The type species of lentivirus and the etiologic agent of acquired immunodeficiency syndrome (AIDS). "The activity of CAMK1D was found to be negatively regulated by HIV-1 infection, which was in correlation with our results, wherein we observed decreased mRNA levels." (PMID 38203551, 2023). "It was also shown that siRNA knockdown of CAMK1D can inhibit HIV-1 infection." (PMID 38203551, 2023).
influenza infection (1 paper, 2019). "In addition, another study suggested that alternatively spliced variants of CAMK1d may protect against influenza infection." (PMID 30669351, 2019).
melanoma (1 paper, 2019). A malignant, usually aggressive tumor composed of atypical, neoplastic melanocytes. "In contrast to BCC and SCC, melanoma biopsies proved to be characterized by transcriptional repression of PRR11 and CAMK1D genes, as indicated by the amplification profiles of the expected 247 and 192 bp PCR products, respectively." (PMID 30795533, 2019).
metabolic syndrome (1 paper, 2017). A cluster of metabolic risk factors for CARDIOVASCULAR DISEASES and TYPE 2 DIABETES MELLITUS. "Our studies indicate Camk1d is genetically regulated in the LH rat, making it an attractive animal model to better understand a pleiotropic role for this gene in important features of the metabolic syndrome." (PMID 28792545, 2017).
narcolepsy (1 paper, 2020). A sleep disorder characterized by a tendency for excessive sleepiness during the day which occurs even after adequate sleep in the nighttime. "In the network,CALM1 bridgesINSR, CAMK1D (the only common gene among the database curated genesets for PD, narcolepsy, and IR), andLRRK2." (PMID 34745571, 2020). "Important genes and pathways that link PD, narcolepsy, and IR areCACNA1C, CAMK1D, BHLHE41, HMGB1, and AGE-RAGE." (PMID 34745571, 2020). "There were 38 shared genes between the PD and narcolepsy genesets.CAMK1D is the only gene common among the 3 genesets for PD, narcolepsy, and IR and it is a Calcium/Calmodulin kinase that is upregulated in PD patients and is also a risk factor for Type 2 diabetes." (PMID 34745571, 2020).
periodontitis (1 paper, 2025). An acute or chronic inflammatory process that affects the tissues that surround and support the teeth. "Periodontitis induced the development of GMPs toward the neutrophil lineage at the expense of monocytic differentiation, as indicated by the dynamic changes in monocytic signature genes (F13a1, Irf8, and Ly86) and neutrophil-associated genes (Camk1d, S100a8, and S100a9) along the trajectory." (PMID 40521205, 2025).
vitiligo (1 paper, 2022). Generalized well circumscribed patches of leukoderma that are generally distributed over symmetric body locations and is due to autoimmune destruction of melanocytes. "Another study also described a decrease in cell proliferation and initiation of apoptosis via caspase-3 and caspase-7 induction due to miR-145 overexpression in non-lesional skin of patients with vitiligo via targeting ROCK1, CAMK1D, and EIF2AK161,106." (PMID 35941163, 2022).
tumor (15 papers, 2017 to 2026). "This region includes CAMK1D, a gene encoding for a key modulator of tumor‐intrinsic immune resistance in humans, which might be beneficial for wolves exposed to high levels of carcinogenic substances produced by anthropic activities." (PMID 41323074, 2025). "CAMK1D knockdown inhibits LNCaP-AI cell proliferation and migration, whereas its overexpression promotes tumor growth and confers androgen independence to LNCaP cells." (PMID 41510165, 2026). "In a mouse orthotopic PCa model, targeting the CAMK1D/AMPK pathway with the siCAM/HLNP nanoformulation suppresses tumor growth by depleting the PCSCs population, achieving a synergistic effect with enzalutamide therapy." (PMID 41419457, 2025). "In contrast, the ‘tumor cells 2’ cluster was characterized by genes associated with protein synthesis (Cmss1, Rpph1, Rps12, Lars2, Ncl2), tumorigenesis (Mt-Rnr2, Hmga2, Mab1b) and cell–cell communication (Gphn, Camk1d, Il31ra, Cmss1, Rpph1), which may be indicative of an inflammatory phenotype." (PMID 39769061, 2024). "The co-expression of Npg, Cd177 and Cybb in the SCLL Ly6g + and Camk1d + neutrophils suggested that they are closely related, which is consistent with both being increased in tumor bearing mice." (PMID 38730491, 2024). "Calcium/calmodulin-dependent protein ID (CAMK1D) is widely expressed in many tissues and involved in tumor cell growth." (PMID 35494053, 2022). "Pan-cancer analysis showed that CAMK1D expression levels were significantly different between multiple tumor tissue and adjacent tissues (or GTEx)." (PMID 35494053, 2022). "Both miRNAs have been previously implicated as mediators of neo-angiogenesis and our analysis shows that when transferred through tumor derived EVs miR-143-3p and miR-145-5p promote tube formation through targeting of CAMK1D in endothelial cells." (PMID 29137392, 2017). "Plxdc2 (Plexin domain containing 2) is less well characterized than Camk1d, but it has been described as highly expressed endothelial tumor marker involved in angiogenesis, and a transmembrane receptor for Pigment Epithelium Derived Factor." (PMID 28792545, 2017). "In addition, some studies have found that CAMK1D was a key regulator of tumor innate immune resistance." (PMID 37254650, 2023). "Furthermore, CAMK1D is known as a negative regulator of angiogenesis, and overexpression of CAMK1D in mouse model suppressed neoangiogenesis and expansion of lung tumor by limiting the tumor’s ability to co-opt the alveolar vasculature." (PMID 37139160, 2023). "This reinforces the fact that camk1d plays different functions in different tumor types." (PMID 35494053, 2022). "Thus, in this study, we determined if the PI3K/AKT/mTOR pathway plays an important role in CAMK1D regulation of tumor function." (PMID 35494053, 2022). "To determine the role of CAMK1D in tumor pathogenesis and development, we studied the relationship between CAMK1D protein and clinicopathological features, including gender, age, recurrence, WHO grade, 1p19q codeletion, subtype, IDH status, and MGMTp methylation in the CGGA dataset." (PMID 35494053, 2022). "Notably, both analyses showed that the PI3K/AKT/mTOR signaling pathway were significantly enriched in tumor-related pathways, and the activation of this pathway was negatively correlated with CAMK1D expression." (PMID 35494053, 2022). "CAMK1D overexpression impairs tumor neoangiogenesis in vivo, thus achieving tumor inhibition." (PMID 34552612, 2021). "The hot genes with the most positive signal events in the normal-specific group were RBPJ, PFKFB3, CAMK1D, ACACB, and WWOX, whereas the hot genes in the tumor-specific group were SLC35F3, PCDH7, NF1, and RAB27B." (PMID 36895481, 2023). "Further molecular analysis showed that Sel‐GemPac treatment caused suppression of calcium/calmodulin‐dependent protein kinase 1 D (CAMK1D), long non‐coding RNA (lncRNA) GM42418 and MALAT1 in most of the clusters of treated KPC tumour cells." (PMID 38131168, 2023).
tumor (continued). "Therefore, the targeted knockdown of CAMK1D is a promising strategy for overcoming ENZR and enhancing anti-tumor immune responses." (PMID 41510165, 2026). "However, based on the tumor expression data in the TCGA and GTEx databases, the expression level of CAMK1D in various tumors is not consistent with its corresponding normal tissues." (PMID 35494053, 2022).
cancer (7 papers, 2015 to 2026). A tumor composed of atypical neoplastic, often pleomorphic cells that invade other tissues. "The function of CAMK1D-mediated depends on the different activation states and binding substrates in different cancers, thus affecting the function and signaling pathways involved in the substrates." (PMID 35494053, 2022). "Recent studies have highlighted the involvement of CAMK1D in cancer, particularly in the context of drug resistance 11; however, its precise role in mediating resistance mechanisms remains unclear." (PMID 41510165, 2026). "Additionally, understudied kinases CAMK1D, PNCK, and NEK3 have mutations with significant pan-cancer prognostic value, with PNCK being mutated frequently in LUAD and NEK3 in COAD and READ (p < 0.05)." (PMID 33205077, 2020). "The understudied multi-functional CaMKs (CAMK1D, CAMK1G, CAMKK1, PNCK) are overexpressed in 12 cancers, with PNCK being overexpressed in 9 alone." (PMID 33205077, 2020). "Since NCI‐60 cancer cell lines with higher MPS1 mRNA levels, but not CAMK1D, showed a weak association with sensitivity to VU‐0365114 treatment, further investigation was conducted to examine the role of MPS1 in the anticancer activity of VU‐0365114." (PMID 37842807, 2024). "This is not identical to the previously reported function of CAMK1D in other cancers." (PMID 35494053, 2022).
CAMK1D also shares sentences with these, for which no sentence is quoted: prostate carcinoma (2 papers); Alzheimer disease (1); anemia (1); attention deficit-hyperactivity disorder (1); cardiovascular disease (1); cognitive disorder (1); colon adenocarcinoma (1); diabetic kidney disease (1); epilepsy (1); erythroleukemia (1); essential hypertension (1); gastroschisis (1); lipodystrophy (1); malnutrition (1); multiple myeloma (1); neural tube defect (1); neuropathy (1); osteoarthritis (1); peripheral artery disease (1); situ breast cancer (1); type 1 diabetes (1); vascular disorder (1).